AK5 (adenylate kinase 5)
Diseases named in the same sentence as AK5 in open-access papers:
AK5 is named in the same sentence as 37 diseases in open-access papers, as found by Europe PMC text mining. Sharing a sentence is not in itself a finding about the gene and the disease. The quoted sentences say what the papers report.
autoimmune encephalitis (5 papers, 2017 to 2026). Inflammation of the brain secondary to an immune response triggered by the body itself. "Limbic encephalitis associated with antibodies against adenylate kinase 5 (AK5) is a rare, non‐paraneoplastic form of autoimmune encephalitis and remains poorly characterized due to its rarity." (PMID 41568974, 2026). "These patients had definite autoimmune encephalitis (AIE) or paraneoplastic neurological syndrome (PNS) and were positive for the following neuronal Abs: Hu (n = 2), Ri (n = 1), AK5 (n = 1), NMDAR (n = 1), and anti-PCA-Tr (n = 1) (middle part)." (PMID 39114659, 2024). "The BR serine/threonine kinase 2 has been identified as a target autoantigen in limbic encephalitis and small cell lung carcinoma and the adenylate kinase 5 has been found in patients with autoimmune encephalitis without known cancer." (PMID 28554330, 2017). "Furthermore, the haplotype DR3 ~ DQ2 has been related to a few autoimmune encephalitis and PNS, principally to neurological syndromes with antibodies against glutamic acid decarboxylase 65 (GAD65) and limbic encephalitis with adenylate kinase 5 (AK5) antibodies." (PMID 38990347, 2024).
lung adenocarcinoma (2 papers, 2019 to 2022). A carcinoma that arises from the lung and is characterized by the presence of malignant glandular epithelial cells. "Unlike other candidate genes, it has been reported that AK5 expression was reduced due to methylation of the promoter region within the CpG islands in lung adenocarcinoma." (PMID 35354498, 2022).
Alzheimer disease (1 paper, 2025). A progressive, neurodegenerative disease characterized by loss of function and death of nerve cells in several areas of the brain leading to loss of cognitive function such as memory and language. "In this study, we observed a reduction in AK5 expression in the hippocampal region of patients with Alzheimer’s disease (AD); however, the underlying cause and timing of this decrease remain unclear." (PMID 41299730, 2025). "Our study identifies a functional role for AK5 in microglia and suggests its potential relevance as a therapeutic target for Alzheimer’s disease (AD)." (PMID 41299730, 2025). "We subsequently focused on adenylate kinase 5 (AK5) to explore its role in neuroinflammation and Alzheimer’s disease pathogenesis." (PMID 41299730, 2025).
autoimmune disease (1 paper, 2017). A disorder resulting from loss of function or tissue destruction of an organ or multiple organs, arising from humoral or cellular immune responses of the individual to their own tissue constituents. "Involvement of AK5 is also seen in neuronal destruction (through T-cell mediated reactions) among patients of limbic encephalitis, another autoimmune disease." (PMID 28505210, 2017).
behavioral disorders (1 paper, 2026). "In addition, anti‐AK5 limbic encephalitis patients more frequently exhibited ≥ 3 of the following symptoms compared to mimics (100% vs. 22.2%, p < 0.05): working memory deficits, new‐onset seizures, behavioral disorders, psychiatric symptoms, and sleep disorders." (PMID 41568974, 2026).
celiac disease (1 paper, 2017). An autoimmune genetic disorder with an unknown pattern of inheritance that primarily affects the digestive tract. "In the context of our study objective, we found insATT in AK5 gene that is perfectly segregated as an autosomal recessive marker in this consanguineous family with celiac disease." (PMID 28505210, 2017).
cholangiocarcinoma (1 paper, 2025). A carcinoma that arises from the intrahepatic biliary tree (intrahepatic cholangiocarcinoma) or from the junction, or adjacent to the junction, of the right and left hepatic ducts (hilar cholangiocarcinoma). "The findings showed that AK5 was strongly expressed in the majority of malignancies, including head and neck squamous cell carcinoma (HNSC) and cholangiocarcinoma (CHOL)." (PMID 40161494, 2025).
colon cancer (1 paper, 2021). "In addition, AK5 DNA hypermethylation decreased in four colon cancer cell samples after treatment with 5-aza, a DNA methyltransferase inhibitor, and expression recovery was observed." (PMID 34135408, 2021). "To identify the relationship between DNA methylation and AK5 expression, we performed qMSP and real-time PCR in one normal colon cell sample (CCD18Co), six colon cancer cell samples (HT-29, SW480, DLD-1, Lovo, HCT116, KM12SM), and two rectal cancer cell samples (SNU-70, SNU-796)." (PMID 34135408, 2021).
colorectal adenocarcinoma (1 paper, 2021). The most common type of colorectal carcinoma. "AK5 expression regulates AMPK/mTOR signalling and may be closely related to metastasis in colorectal adenocarcinoma." (PMID 34135408, 2021).
colorectal cancer (1 paper, 2021). A primary or metastatic malignant neoplasm that affects the colon or rectum. "However, the role of AK5 in colorectal cancer (CRC) has not been reported." (PMID 34135408, 2021).
dementia (1 paper, 2025). Loss of intellectual abilities interfering with an individual's social and occupational functions. "Future studies in larger cohorts are needed to clarify the compound risk associated with AK5 SNPs in dementia." (PMID 41299730, 2025).
dyslipidemia (1 paper, 2025). "Given AK5’s role in energy metabolism, such variants may intensify dyslipidemia and microglial dysfunction, exerting stronger effects in women." (PMID 41299730, 2025).
encephalitis (1 paper, 2026). An acute inflammatory process affecting the brain parenchyma. "Given the potential for serious side effects associated with immunotherapy and the broad differential diagnosis for AE, improving diagnostic specificity for anti‐AK5 encephalitis is essential for clinical practice." (PMID 41568974, 2026). "We aim to assess the frequency of anti‐AK5 encephalitis overdiagnosis and identify common diagnostic pitfalls." (PMID 41568974, 2026). "In conclusion, our study demonstrates that mimics of anti‐AK5 encephalitis are common, and misdiagnosis remains a significant challenge." (PMID 41568974, 2026). "Our findings show that anti‐AK5 encephalitis mimics are diverse and significantly outnumber confirmed anti‐AK5 encephalitis case diagnoses, with misdiagnosis occurring approximately six times more frequently." (PMID 41568974, 2026). "We identified key clinical and preclinical features that can aid in distinguishing anti‐AK5 encephalitis from mimics." (PMID 41568974, 2026). "In this retrospective cohort study, we identified common anti‐AK5 encephalitis mimics and highlighted key red flags to prevent misdiagnosis." (PMID 41568974, 2026). "Patients with atypical clinical phenotypes pose significant diagnostic challenges and are at higher risk of being either misdiagnosed with or overlooked for anti‐AK5 encephalitis." (PMID 41568974, 2026). "Beyond clinical presentation, we identified several red flags that may aid in distinguishing anti‐AK5 encephalitis from its mimics." (PMID 41568974, 2026). "However, our understanding of the clinical spectrum of anti‐AK5 encephalitis remains incomplete, particularly in East Asian populations, where few large cohort studies exist." (PMID 41568974, 2026). "Reported cases, primarily from North America and Europe, suggest that anti‐AK5 encephalitis typically presents with subacute anterograde amnesia, often without seizures, and may be preceded by a prodromal phase of asthenia or mood disturbances." (PMID 41568974, 2026). "This study aims to determine the prevalence of anti‐AK5 encephalitis misdiagnosis through retrospective case analysis, and to identify commonly encountered mimics and diagnostic red flags that may help clinicians avoid misdiagnosis." (PMID 41568974, 2026).
ependymoma (1 paper, 2024). A WHO grade II, slow growing tumor of children and young adults, usually located intraventricularly. "BST1, FLG, KANK4, and SHISA9 were significantly higher expressed in SP-EPN subtype A compared to all other ependymomas, whereas AK5, CFTR, RASSF6, and TBX22 showed high expression in subtype B." (PMID 38265489, 2024).
gastric cancer (1 paper, 2022). A primary or metastatic malignant neoplasm involving the stomach. "AK5 was reported as a new prognosis marker that promotes autophagy and proliferation in human gastric cancer." (PMID 35372462, 2022).
Hyperglycemia (1 paper, 2011). An increased concentration of glucose in the blood. "The cardiogenic growth factor TGF-β promoted AK1 expression, while knockdown of AK1, AK2 and AK5 activities with siRNA or suppression by hyperglycemia disrupted cardiogenesis compromising mitochondrial and myofibrillar network formation and contractile performance." (PMID 21556322, 2011).
leukemia (1 paper, 2021). A malignant (clonal) hematologic disorder, involving hematopoietic stem cells and characterized by the presence of primitive or atypical myeloid or lymphoid cells in the bone marrow and the blood. "Next, AK5 is a member of adenylate kinase family that was previous shown to be highly expressed in leukemia stem cells (LSCs) compared to human hematopoietic stem cells (HSCs), indicating potential therapeutic targets for quiescent and chemotherapy-resistant human LSCs." (PMID 34202615, 2021).
lymph node metastasis (1 paper, 2021). "Survival analyses of AK5 expression along with patient age, gender, tumour size, location, differentiation, stage, lymph node metastasis, resection margin status, and recurrence were performed." (PMID 34135408, 2021).
marginal zone lymphoma (1 paper, 2026). A usually indolent mature B-cell lymphoma, arising from the marginal zone of lymphoid tissues. "One patient with definite anti‐AK5 limbic encephalitis had extranodal marginal zone lymphoma of mucosa‐associated lymphoid tissue." (PMID 41568974, 2026).
metastatic cancer (1 paper, 2021). A carcinoma which has spread from the original site of growth to another anatomic site. "Furthermore, AK5 expression was compared between adjacent normal and primary CRC and metastatic cancer tissues." (PMID 34135408, 2021). "Although it was not clinically significant, it was observed that AK5 expression decreased in metastatic cancer tissues compared to primary CRC tissues and adjacent normal tissues (P = 0.068, P = 0.218, respectively)." (PMID 34135408, 2021).
prostate carcinoma (1 paper, 2025). A carcinoma that arises from epithelial cells of the prostate gland. "This study constructed a prognostic model with clinical potential and preliminarily confirmed the oncogenic role of AK5 in prostate cancer." (PMID 41179286, 2025). "Univariate COX regression analysis utilizing the Ruijin prostate cancer dataset indicated a correlation between AK5 expression level and patient prognosis." (PMID 41179286, 2025). "Functional experiments confirm that the knockdown of AK5 obviously inhibits the prostate cancer cells’ proliferation and clonogenic ability, while its overexpression promotes malignant phenotypes." (PMID 41179286, 2025). "Additionally, the prognostic gene Adenylate Kinase 5 (AK5) was analyzed in prostate cancer tissue microarrays from Ruijin Hospital." (PMID 41179286, 2025). "The findings indicate that focusing on the immunological metabolic axis and the AK5 gene may offer novel approaches for prostate cancer treatment." (PMID 41179286, 2025). "Furthermore, experimental evidence has preliminarily confirmed the oncogenic role of AK5 in prostate cancer." (PMID 41179286, 2025). "The functional role of the AK5 gene was validated through knockdown and overexpression experiments in four prostate cancer cell lines, employing cell proliferation assays, colony formation assays, and both xenograft models in nude mice and patient-derived xenograft models." (PMID 41179286, 2025). "Our study reveals the oncogenic role of AK5 in prostate cancer." (PMID 41179286, 2025).
cancer (6 papers, 2017 to 2025). A tumor composed of atypical neoplastic, often pleomorphic cells that invade other tissues. "Moreover, the AK5 expression is associated with cancer stages and types and is an independent prognostic factor." (PMID 36982634, 2023). "Although AK5 expression has been investigated in a pan-cancer context, its role in PRAD remains poorly understood." (PMID 40161494, 2025). "We conducted a correlation analysis between AK5 and several immune checkpoint molecules typically expressed on cancer cells and/or APCs, such as PD-L1, CD155, and GAL-9." (PMID 40161494, 2025). "For instance, the hypermethylation of the AK5 promoter has been reported in certain cancers, leading to reduced AK5 expression." (PMID 41299730, 2025). "A three-gene signature model (KCNK3, AK5, and ARHGEF38) was established, and the model was significantly associated with cancer-related pathways, overall survival (OS), and tumor microenvironment (TME)-related immune cells in PCa." (PMID 35372462, 2022). "Finally, IHC analysis of AK5 was performed using 615 CRC tissues, 25 adjacent normal tissues, and 26 liver and lung metastasized cancer tissues to find the relationship between AK5 expression and clinicopathological features." (PMID 34135408, 2021). "The inclusion of genes like AK5, CDC20, and TFF3, which have established roles in cancer cell proliferation and metastasis, underscores their importance in a predictive model." (PMID 40161494, 2025). "A three-gene signature model (KCNK3, AK5, and ARHGEF38) was constructed, and the model was significantly related to cancer-related pathways, overall survival, and TME cells in PCa." (PMID 35372462, 2022). "Using TCGA pan-cancer data, we examined the expression of AK5 in tumor versus normal tissues across a variety of cancer types." (PMID 40161494, 2025).
tumor (6 papers, 2021 to 2025). "Aberrant expression of AK5 is closely linked to metabolic imbalance, neuroprotection, and tumor progression, suggesting its potential as a biomarker or therapeutic target for energy metabolism-related diseases." (PMID 41179286, 2025). "Further research can concentrate on assessing tumor cell metabolism following knockdown or overexpression of the gene AK5." (PMID 41179286, 2025). "We also utilized cell lines with knockdown and overexpression of AK5 and re-administered apigenin to evaluate its impact on the proliferative capacity of tumor cells." (PMID 41179286, 2025). "This knockdown resulted in increased tumor cell apoptosis, with the apoptotic cell rate significantly higher in the si-AK5 group (17.78% ± 0.46%) compared to the si-NC group (24.69% ± 1.62%, p = 0.0021)." (PMID 40161494, 2025). "EZH2 was primarily located in monocyte/macrophage cells, whereas the expression of AK5 was detected in fibroblasts, epithelial cells, and tumor cells." (PMID 40161494, 2025). "Clinicopathologic factors were evaluated for correlation with AK5 expression, and tumour differentiation showed significant correlation with AK5 expression (P = 0.026)." (PMID 34135408, 2021). "For instance, extracellular matrix components secreted by myofibroblasts, such as collagen, may promote tumor invasion through integrin signaling pathways, while AK5-mediated energy metabolism reprogramming may further exacerbate this process." (PMID 41179286, 2025). "Conversely, the LNCaP and DU145 cell lines exhibited a marked increase in absorbance changes following AK5 overexpression compared to their non-overexpressing controls, suggesting an enhancement in the proliferative capacity of the tumor cells after AK5 overexpression." (PMID 41179286, 2025). "Additionally, single-cell transcriptomic analysis reveals that AK5 is significantly expressed in myofibroblasts, suggesting its potential role in modulating tumor-stroma interactions that influence the metabolic state of the microenvironment." (PMID 41179286, 2025). "The downregulation of CD276 following a reduction in AK5 expression in tumor cells suggests that targeting AK5 may enhance the efficacy of immunotherapies that leverage the CD276 checkpoint strategy." (PMID 40161494, 2025). "The analysis results showed that knocking down AK5 significantly inhibited tumor growth, while rescuing AK5 expression after knockdown could eliminate this inhibitory effect." (PMID 41179286, 2025). "It was observed that the absorbance changes in the VCaP and MDAPCa2b cell lines, following AK5 knockdown, were significantly reduced compared to the non-knockdown counterparts, indicating a decline in the proliferative capacity of the tumor cells post-knockdown of AK5." (PMID 41179286, 2025). "Colony formation assays indicated that inhibiting AK5 could reduce the proliferative ability of tumor cells." (PMID 41179286, 2025). "However, in gastric cancer, patients with high AK5 levels in tumor tissue have significantly shorter survival rates compared to that in the low expression group." (PMID 36982634, 2023). "Notably, in vivo results indicate that a reduced AK5 expression is required for tumor growth." (PMID 36982634, 2023). "Genes such as AK5 and MICU3 showed expression changes in pretreatment tumor tissue, and posttreatment blood may be indicators of treatment response." (PMID 36697401, 2023). "Its expression in colon adenocarcinoma tumor tissue is lower than that in noncancerous tissue; particularly, patients with high AK5 expression have longer overall survival than those with low expression." (PMID 36982634, 2023). "However, no significant changes in AK5 methylation or expression were observed with tumour grades or location of CRC cells." (PMID 34135408, 2021).
neurodegenerative disease (2 papers, 2025). A disorder of the central nervous system characterized by gradual and progressive loss of neural tissue and neurologic function. "Previous studies have indicated that AK5 is downregulated in neurodegenerative diseases and is associated with disturbances in brain energy metabolism." (PMID 41179286, 2025). "Changes in AK5 expression may be related to age, as AD is a neurodegenerative disease strongly associated with aging." (PMID 41299730, 2025). "AK5, a less studied isoform, has not been extensively researched in the context of neurodegenerative diseases." (PMID 41299730, 2025).
neurological disorder (2 papers, 2024 to 2026). "Such as was done for astrocytes, we enrolled six patients with definite neuron-specific Ab-associated neurological disorders: anti-AK5+ AIE/PNS (n = 1), anti-PCA-Tr+ AIE/PNS (n = 1), anti-NMDAR+ AIE/PNS (n = 1), anti-Hu+ AIE/PNS (n = 2), and anti-Ri+ AIE/PNS (n = 1)." (PMID 39114659, 2024). "In 18 of the 21 anti‐AK5 antibody‐positive patients (85.7%), the final diagnosis was revised to an alternative neurological disorder." (PMID 41568974, 2026).
brain disorder (1 paper, 2026). A disease affecting the brain or part of the brain. "AK5‐antibody might be occurring as a bystander effect in other brain disorders, or result from the production of cross‐reactive IgG, or represent an epiphenomenon of neuronal injury or a remnant of a prior immune event, rather than a direct cause of pathology." (PMID 41568974, 2026).
AK5 also shares sentences with these, for which no sentence is quoted: asthma (1 paper); Brain atrophy (1); COVID-19 (1); epilepsy (1); head and neck squamous cell carcinoma (1); hippocampal atrophy (1); memory impairment (1); ovarian carcinoma (1); rectal cancer (1); sleep disorder (1); small cell lung carcinoma (1).